SORBS2 (sorbin and SH3 domain containing 2)
Description:
Adapter protein that plays a role in the assembling of signaling complexes, being a link between ABL kinases and actin cytoskeleton. Can form complex with ABL1 and CBL, thus promoting ubiquitination and degradation of ABL1. May play a role in the regulation of pancreatic cell adhesion, possibly by acting on WASF1 phosphorylation, enhancing phosphorylation by ABL1, as well as dephosphorylation by PTPN12. Isoform 6 increases water and sodium absorption in the intestine and gall-bladder.
Synonyms: ArgBP2; KIAA0777; PRO0618
Tractability: Antibody: UniProt places it where antibodies can reach, with high confidence; its Gene Ontology location is reachable by antibodies, with medium confidence. PROTAC: UniProt records ubiquitination sites on it; its protein half-life has been measured.
Gene: Protein-coding gene on chromosome 4 (185,585,444 to 185,956,652, reverse strand). Ensembl gene ENSG00000154556.
Subcellular location: Cytoplasm, perinuclear region; Apical cell membrane; Cell junction, focal adhesion; Cell projection, lamellipodium
Gene Ontology:
Molecular function: protein binding; RNA binding; cytoskeletal anchor activity; protein-macromolecule adaptor activity; structural constituent of cytoskeleton; structural constituent of muscle
Biological process: cell growth involved in cardiac muscle cell development; cytoskeleton organization; Notch signaling pathway
Cellular component: apical plasma membrane; actin cytoskeleton; dendrite; neuronal cell body; nucleus; plasma membrane; synapse; Z disc; focal adhesion; lamellipodium; perinuclear region of cytoplasm
Genetic constraint (gnomAD): Loss-of-function variants: 32 observed, 71.71 expected, observed/expected ratio (o/e) 0.45, 90% interval 0.34 to 0.6. The upper end of that interval is the gene's LOEUF score, 0.6, which puts it in group 2 of 6, group 1 being the genes least tolerant of losing a copy. Missense variants: 1,099 observed, 1,126.1 expected, observed/expected ratio (o/e) 0.98, 90% interval 0.93 to 1.03. Synonymous variants: 418 observed, 428.94 expected, observed/expected ratio (o/e) 0.97, 90% interval 0.9 to 1.06.
Homologues: Orthologues: chimpanzee SORBS2 (90% identical), rat Sorbs2 (88% identical), dog SORBS2 (84% identical), guinea pig SORBS2 (84% identical), mouse Sorbs2 (84% identical), rabbit SORBS2 (84% identical), pig SORBS2 (83% identical), tropical clawed frog sorbs2 (64% identical), macaque SORBS2 (53% identical), zebrafish sorbs2b (51% identical), zebrafish sorbs2a (47% identical), Caenorhabditis elegans sorb-1 (13% identical), and 2 more. Paralogues in human: SORBS1 (23% identical), SORBS3 (16% identical), SH3D19 (13% identical), SH3RF3 (9% identical), SH3RF1 (9% identical), SH3RF2 (6% identical), SH3GL1 (6% identical), SH3GL2 (5% identical), SH3GL3 (5% identical), NCF4 (5% identical), SH3GLB2 (5% identical), SH3GLB1 (5% identical).
Diseases named in the same sentence as SORBS2 in open-access papers:
SORBS2 is named in the same sentence as 56 diseases in open-access papers, as found by Europe PMC text mining. Sharing a sentence is not in itself a finding about the gene and the disease. The quoted sentences say what the papers report.
ovarian carcinoma (14 papers, 2018 to 2024). A malignant neoplasm originating from the surface ovarian epithelium. "Among the 91 gene transcripts potentially bound and stabilized by SORBS2, seven transcripts that encode secreted proteins attracted our attention since we focus on potential interactions between ovarian cancer cells and the tumor microenvironment during the metastatic process." (PMID 29548303, 2018). "The most well studied SORBS protein is SORBS2, which functions as a tumor suppressor in cervical, ovarian cancer and hepatocellular carcinoma (HCC)." (PMID 37038184, 2023). "PIK3R3 expression was lower in USP4, SPTBN1, and SORBS2-mutant ovarian cancer patients than in ovarian cancer patients with wild type genes." (PMID 35761259, 2022). "In ovarian cancer, SORBS2 suppresses metastatic colonization of cancer cells by eliciting a tumor-suppressive immune microenvironment." (PMID 34692669, 2021). "Consistent with the results from the AOCS and West China cohort, Kaplan-Meier analysis of ovarian cancer patients in CSIOVDB also showed that SORBS2 expression was correlated with overall survival and progression-free survival of ovarian cancer patients." (PMID 29548303, 2018). "Our findings have identified a functional role of SORBS2 and its stabilized transcripts in ovarian cancer progression, deepening our understanding of the molecular complexities of ovarian cancer metastasis." (PMID 29548303, 2018). "In this study, we elucidate a mechanism through which the RBP SORBS2 mediates its suppressive effect in ovarian cancer metastatic colonization." (PMID 29548303, 2018). "We performed qRT-PCR to examine the mRNA levels of SORBS2 in these subgrouped ovarian cancer cell lines." (PMID 29548303, 2018). "We observed that SORBS2 knockdown significantly promoted in vivo metastatic colonization of ovarian cancer cells in mice, including increasing the number of metastatic nodules and the ascites volume within the abdominal cavity." (PMID 29548303, 2018). "We found that SORBS2 expression was lower in stage I ovarian cancer patients compared with stage II–IV ovarian cancer patients." (PMID 29548303, 2018). "We subsequently investigated the molecular mechanisms through which SORBS2 mediates suppression of metastatic colonization of ovarian cancer." (PMID 29548303, 2018). "We next examined the protein expression level of SORBS2 in clinical specimens of ovarian cancer and normal ovary using immunohistochemistry analysis." (PMID 29548303, 2018). "By enhancing the stability of these gene transcripts, SORBS2 suppresses ovarian cancer invasiveness and affects monocyte to myeloid-derived suppressor cell and M2-like macrophage polarization, eliciting a tumor-suppressive immune microenvironment." (PMID 29548303, 2018). "The expression of SORBS2 in CCNE1high ovarian cancer specimens is significantly lower compared with that in CCNE1low ovarian cancer specimens." (PMID 29548303, 2018). "We identified the RBP sorbin and SH3 domain containing 2 (SORBS2) as a metastasis suppressor in ovarian cancer." (PMID 29548303, 2018). "In this study, we identify that the RBP sorbin and SH3 domain containing 2 (SORBS2) is a potent suppressor of ovarian cancer metastatic colonization." (PMID 29548303, 2018). "The results showed that SORBS2 was significantly down-regulated in ovarian cancer compared with normal ovary." (PMID 29548303, 2018). "Through this analysis, we identified 91 genes (accounting for 8.39% of all the transcripts bound by SORBS2) as potential regulators of ovarian cancer metastasis downstream of SORBS2." (PMID 29548303, 2018). "Our study shows that supernatants of both WFDC1- and IL-17D-overexpressed, SORBS2-depleted ovarian cancer cells significantly reduced the amount of HLA-DRlo/neg CD14+ cells in vitro." (PMID 29548303, 2018). "SORBS2 has been reported to function as a tumor suppressor in hepatocellular carcinoma, gastric cancer, pancreatic cancer, clear cell renal cell carcinoma and ovarian cancer." (PMID 38177123, 2024).
ovarian carcinoma (continued). "Interestingly, SORBS2 has been shown to suppress metastatic spread and to promote a tumor-suppressive microenvironment in ovarian cancer models in vivo." (PMID 36195845, 2022). "A recent study reported SORBS2 could suppress metastatic colonization in ovarian cancer through multiple mechanisms." (PMID 33934539, 2021). "Moreover, we searched the prognostic prediction values of these two genes in the Australian Ovarian Cancer Study (AOCS) dataset (GSE9891) and found that only SORBS2 was significantly correlated with overall survival of ovarian cancer patients." (PMID 29548303, 2018). "Second, considering that one of the most important functions of RBPs is the regulation of RNA stability, we performed transcriptome-wide analysis of RNA stability to identify the RNAs that SORBS2 could stabilize in ovarian cancer metastasis." (PMID 29548303, 2018). "Immunohistochemical analysis of Ki-67 in tumor tissues in the control group and the SORBS2 knockdown group did not demonstrate significant difference, indicating that SORBS2 knockdown primarily hijacked metastatic programs instead of proliferation-related signaling in ovarian cancer." (PMID 29548303, 2018). "Moreover, we found that SORBS2 expression was correlated with clinical prognosis in a West China cohort of ovarian cancer, consistent with our findings for the AOCS dataset." (PMID 29548303, 2018). "We next attempted to identify SORBS2-bound transcripts that could mediate its effects on ovarian cancer metastasis." (PMID 29548303, 2018). "We observed that stable overexpression of either WFDC1 or IL-17D or a combination of both significantly decreased the invasive capacity of SORBS2-depleted ovarian cancer cells compared with control, revealed by Transwell chamber analysis and wound healing analysis." (PMID 29548303, 2018). "Our study demonstrated that forced expression of IL-17D in SORBS2-depleted ovarian cancer cells could also significantly reduce ovarian cancer metastatic colonization." (PMID 29548303, 2018). "We treated SORBS2-depleted or control A2780s ovarian cancer cells with α-amanitin and isolated RNA." (PMID 29548303, 2018). "First, to identify endogenous RNA targets of SORBS2 in ovarian cancer cells, we performed high-throughput RNA immunoprecipitation sequencing (RIP sequencing) in A2780s ovarian cancer cell lines expressing Flag-tagged SORBS2 and control A2780s ovarian cancer cells." (PMID 29548303, 2018). "However, conditioned media from either WFDC1 or IL-17D overexpressed, SORBS2-depleted ovarian cancer cells significantly reduced the amount of HLA-DRlo/neg CD14+ cells." (PMID 29548303, 2018). "By contrast, conditioned media from either WFDC1 or IL-17D overexpressed SORBS2-depleted ovarian cancer cells could obviously reverse this process." (PMID 29548303, 2018). "Moreover, the in vivo metastatic colonization potential of SORBS2-depleted ovarian cancer cells was also remarkably reduced after overexpression of either WFDC1 or IL-17D or a combination of them." (PMID 29548303, 2018). "Subsequently, we examined the metastasis-suppressive role of SORBS2 in ovarian cancer in vivo." (PMID 29548303, 2018). "We further examined the expression of SORBS2 in different ovarian cancer datasets and found that SORBS2 expression was uniformly down-regulated in ovarian cancer tissues compared with either normal ovary tissues or borderline ovarian tumor tissues in four publicly available datasets." (PMID 29548303, 2018). "To define the potential phenotypes displayed by SORBS2-depleted cells that could enhance metastatic activity in vitro, we assessed the ability of SORBS2-knocked down ovarian cancer cells to migrate through Transwell chamber." (PMID 29548303, 2018). "We next determined whether reconstituting the expression of these genes in cells depleted of SORBS2 could reverse the enhanced metastatic phenotype of ovarian cancer in vitro and in vivo." (PMID 29548303, 2018).
ovarian carcinoma (continued). "Moreover, CSIOVDB analysis revealed that SORBS2 expression was significantly down-regulated in ovarian cancers with higher differentiation degree, more advanced FIGO stage, and refractory or resistant disease." (PMID 29548303, 2018). "PI/Annexin V flow cytometry analysis also revealed that the apoptosis rate in the metastasized tissues in the SORBS2-knockdown group was significantly lower than that in the control group, revealing an apoptosis resistance-promoting role of SORBS2 knockdown in ovarian cancer." (PMID 29548303, 2018). "Moreover, we further analyzed SORBS2 expression with other clinical parameters that might influence the prognosis of ovarian cancer patients in the Tothill dataset (GSE9899), including patient age and disease stage." (PMID 29548303, 2018). "In detail, reconstituting the expression of either WFDC1 or IL-17D or a combination of both in SORBS2-knockdown ovarian cancer cells significantly reduced the number of metastatic nodules and ascites volume compared with control SORBS2-knockdown ovarian cancer cells in vivo." (PMID 29548303, 2018). "Thus, we conclude that the cancer-derived SORBS2-stabilized secretome could potently suppress ovarian cancer metastasis and modulate the accumulation of tumor-promoting myeloid cells in vivo." (PMID 29548303, 2018). "More interestingly, we found that a SORBS2-stablized secretome in ovarian cancer could condition the tumor microenvironment to be favorable for cancer metastasis, via affecting the polarization of monocytes to myeloid-derived suppressor cells (MDSCs) and M2-like macrophages." (PMID 29548303, 2018). "Immunohistochemistry analysis revealed that in ovarian cancer specimens with high SORBS2 expression, expression of WFDC1 and IL-17D was also reduced in both primary and metastatic foci of ovarian cancer." (PMID 29548303, 2018). "The steady-state levels of these seven transcripts were assessed in two SORBS2-knockdown ovarian cancer cell lines and we identified the mRNAs of two genes, WFDC1 and IL-17D, as exhibiting reduced steady-state levels upon SORBS2 knockdown in both cell lines." (PMID 29548303, 2018). "SORBS2 depletion significantly enhanced migration ability of both A2780s and SKOV-3 ovarian cancer cells through Transwell chamber analysis." (PMID 29548303, 2018). "Consistently, wound healing analysis demonstrated that knockdown of SORBS2 expression in A2780s and SKOV-3 ovarian cancer cells significantly enhanced their metastatic potential." (PMID 29548303, 2018). "We designed two short-hairpin RNAs (shRNA) to stably silence SORBS2 expression in both SKOV-3 and A2780s ovarian cancer cells." (PMID 29548303, 2018). "We found that only SORBS2 and MEX3D gene knock down significantly increased the metastatic colonization capacity of ovarian cancer." (PMID 29548303, 2018). "SORBS2 enhanced the stability of WFDC1 and IL‐17D and inhibited the invasion in ovarian cancer." (PMID 34890108, 2022). "Meanwhile, M2-like TAM polarization could be repressed by sorbin and SH3 domain containing 2 (SORBS2) through stabilizing WAP four-disulfide core domain 1 (WFDC1) and IL-17D in ovarian cancer." (PMID 36035994, 2022). "Among all these RBP genes, only four showed deletion in more than 5% of TCGA ovarian cancer samples, including transcription factor BTF3, sorbin and SH3 domain-containing protein 2 (SORBS2), cold-inducible RNA-binding protein (CIRBP), and RNA-binding protein MEX3D (MEX3D)." (PMID 29548303, 2018). "Given that SORBS2 knockdown reduced the stability and subsequent abundance of WFDC1 and IL-17D transcripts, we attempted to characterize the functional roles of these two genes in metastatic colonization of ovarian cancer cells." (PMID 29548303, 2018). "First, we did not observe enhanced primary tumor growth rates in SORBS2 knockdown ovarian cancer cells compared with control cells in vivo (data not shown)." (PMID 29548303, 2018).
ovarian carcinoma (continued). "Thus, SORBS2-bound transcripts of WFDC1 and IL-17D served as potent metastatic suppressors in ovarian cancer." (PMID 29548303, 2018). "A negative correlation between age of ovarian cancer patients and SORBS2 was also observed." (PMID 29548303, 2018). "Interestingly, we found that enforced expression of ∆SoHo and ∆SH3 plasmids significantly suppressed ovarian cancer migration in vitro compared to WT SORBS2 protein while enforced expression of ∆Znf plasmids did not inhibit ovarian cancer cell migration." (PMID 29548303, 2018).
cardiac hypertrophy (7 papers, 2017 to 2024). "Exosome-derived miR-21-3p reportedly triggers cardiac hypertrophy via sorbin and SH3 domain-containing protein 2 (SORBS2) and PDZ and LIM domain 5 (PDLIM5)." (PMID 38355681, 2024). "Arginine binding protein 2 (SORBS2) and ENH are reported to be associated with myocardial hypertrophy." (PMID 33632070, 2021). "miR-21-3p-enriched exosomes are also released by cardiac fibroblasts in the mouse model of cardiac hypertrophy, and exosomal miR-21-3p silences SORBS2 and PDLIM5 in cardiomyocytes resulting in cardiac hypertrophy." (PMID 32596327, 2020). "Among them, Csrp3, Pdlim5, Sorbs2, Rcan1, and Acta1, which were related to cardiac hypertrophy and remodeling, were upregulated and modified by at least one active histone mark." (PMID 33330655, 2020). "Additionally, exosome-derived miR-21-3p has been identified as a key mediator in cardiac hypertrophy through its regulatory impact on sorbin and SH3 domain containing 2 (SORBS2) and PDZ and LIM domain 5 (PDLIM5)." (PMID 38398032, 2024).
gastric cancer (5 papers, 2018 to 2024). A primary or metastatic malignant neoplasm involving the stomach. "The expression levels of CDKN3 and DLGAP5 were markedly increased, whereas those of SPARCL1 and SORBS2 were decreased in 60 human gastric cancers." (PMID 34893582, 2021). "In addition, the mRNA expression levels of CDKN3, DLGAP5, SPARCL1, and SORBS2 were positively correlated with CNAs in our gastric cancer samples." (PMID 34893582, 2021). "Since depletion of NKX6.3 in gastric epithelial cell lines induced CNAs and abnormal expression of SORBS2, SPARCL1, DLGAP5, and CDKN3, we examined NKX6.3 expression and these genes’ CNAs and expression in gastric cancer tissues." (PMID 34893582, 2021).
hepatocellular carcinoma (5 papers, 2020 to 2024). A malignant tumor that arises from hepatocytes. "SORBS2, which is highly expressed in the normal human tissues, is strongly repressed during the progression and metastasis of cervical carcinogenesis, hepatocellular carcinoma, and pancreatic cancer." (PMID 33311452, 2020). "Moreover, the RBP SORBS2 restricts hepatocellular carcinoma tumourigenesis and metastasis through enhancing RORA mRNA stability." (PMID 34861864, 2021). "In addition, SORBS2 has been identified as an RBP to suppress metastasis of hepatocellular carcinoma and ovarian cancer." (PMID 33311452, 2020).
pancreatic cancer (5 papers, 2011 to 2024). "Recent data indicate that SORBS2 might be a tumor suppressor since its expression is decreased during pancreatic cancer transformation and its overexpression in metastatic cell lines inhibits cellular migration." (PMID 38342435, 2024).
Sepsis (5 papers, 2020 to 2025). Sepsis is defined as life-threatening organ dysfunction caused by a dysregulated host response to infection. "According to current reports, miR‐21‐3p is also an important miRNA involved in immune regulation in inflammatory diseases; it regulates intestinal immunity by targeting downstream MTDH and SORBS2 to modulate sepsis‐induced cardiac inflammation." (PMID 40845083, 2025). "H19 sponged miR-93-5p to promote SORBS2 expression.H19 suppressed sepsis-induced myocardial injury via regulation of the miR-93-5p/SORBS2 axis." (PMID 40041174, 2025). "Next, miR‐146a inhibits sepsis‐induced myocardial dysfunction by targeting ErbB4 (An, Feng, Xi, Xu, & Sun, 2018), and miR‐21‐3p modulates sepsis‐induced cardiac dysfunction by targeting SORBS2." (PMID 32369227, 2020).